CXCR4 (C-X-C motif chemokine receptor 4)
Diseases named in the same sentence as CXCR4 in open-access papers (continued):
Sharing a sentence is not in itself a finding about the gene and the disease.
lung carcinoma (continued). "CXCR4/CXCL12 signalling is involved in lung carcinoma metastasis, where CXCR4 is a chemokine that is universally upregulated in tumour cells which migrate to the bone." (PMID 40852716, 2025). "This promotes a positive feedback loop in which lung cancer cells upregulate the CXCL12/CXCR4 pathway to further increase ERα expression." (PMID 41463203, 2025). "CXCR4 expression in lung cancer has been related to the enrichment of lung CSC with a capacity for self-renewal, metastasis, and resistance to treatment." (PMID 41383468, 2025). "Chittasupho and colleagues demonstrated that conjugating the CXCR4-targeting peptide LFC131 onto PLGA NPs significantly enhanced the delivery of doxorubicin to CXCR4-expressing A549 lung cancer cells." (PMID 41012430, 2025). "In a study, it was found that lung cancer can be made more sensitive to drugs with the help of blocking CXCR4." (PMID 41383468, 2025). "This review systematically summarizes the biological functions and molecular mechanisms of the CCR9/CCL25 and CXCL12/CXCR4 axes in lung cancer." (PMID 40607416, 2025). "Radiotherapy remains a cornerstone of lung cancer treatment, yet CXCR4-mediated DNA damage repair mechanisms contribute to radioresistance, allowing tumor cells to survive and repopulate following radiation exposure." (PMID 41383468, 2025). "CXCR4-expressing lung cancer cells are more metastatic because the receptor promotes chemotactic migration towards CXCL12-enriched sites, allowing invasion, extravasation, and colonization." (PMID 41383468, 2025). "The role of CXCR4 in lung cancer pathogenesis and development is critically reviewed, the most recent results on plerixafor inhibition of CXCR4 are summarized, and new, potential strategies for combination treatment of CXCR4 with other inhibitors are explored." (PMID 41383468, 2025). "Elevated CXCR4 expression in lung cancer has been correlated with enhanced tumor aggressiveness as well as a poor prognosis in tandem with both enhanced therapy resistance to chemotherapy and ICI therapy." (PMID 41383468, 2025). "The therapeutic targeting of CXCR4 is of great interest since this axis plays a key part in the development of lung cancer." (PMID 41383468, 2025). "Plerixafor, as a CXCR4 targeted treatment for lung cancer, is well supported by preclinical or early clinical evidence as a potential therapeutics for lung cancer in combination with chemotherapy, radiotherapy, and immunotherapy." (PMID 41383468, 2025). "CXCR4-mediated signaling in lung cancer contributes to T-cell exclusion, immune evasion, and recruitment of immunosuppressive cells, which suppress anti-tumor immunity." (PMID 41383468, 2025). "Having been shown to overexpress CXCR4, lung cancer is a very strong predictor of poor prognosis, increased metastatic potential, and decreased survival rates, making it a good candidate target for a treatment intervention." (PMID 41383468, 2025). "For the clinical benefits of CXCR4 targeted therapy in lung cancer management, the patient selection strategies, combination therapy approaches, and optimized drug formulations will be moving forward." (PMID 41383468, 2025). "Our previous research highlighted the clinical relevance of transcription factor JunB (JUNB), C‐X‐C chemokine receptor type 4 (CXCR4), and programmed cell death 1 ligand 1 (PD‐L1) in breast and non‐small cell lung cancer (NSCLC) patients." (PMID 39575761, 2025). "This is achieved through the upregulation of C-X-C motif chemokine receptor 4 (CXCR4), which is involved in the growth and metastasis of lung cancer cells." (PMID 39349424, 2024). "Clinical samples from lung cancer patients have demonstrated the co-expression of CXCR4, p-STAT3, and VEGF-A, suggesting a potential role in tumor progression and angiogenesis in non-small cell lung cancer (NSCLC)." (PMID 38920657, 2024).
lung carcinoma (continued). "Alternatively activated macrophages expressing MRC1, TIE2 and CXCR4 also stimulate tumor relapse in a model with Lewis lung carcinoma cells and promote angiogenesis via VEGFA secretion." (PMID 38532508, 2024). "An exploratory analysis of a phase II study (NCT01439568) assessed the utility of CXCR4 expression in circulating tumor cells as a prognostic biomarker in 89 lung cancer patients." (PMID 39114657, 2024). "Given that lung tissue is a common site of primary lung cancer development as well as metastasis from tumors outside the lungs, treatments using chemokines such as CXCR4 appear promising." (PMID 39114657, 2024). "In lung cancer cells A549 and H460, microarray analysis revealed that Slug is a downstream effector molecule of CXCR4/STAT3 signaling." (PMID 39195486, 2024). "CXCR4 antagonistic nanoparticles have also been designed to enhance the response rate of anti–PD-L1 therapy to treat lung cancer." (PMID 39114657, 2024). "Previous studies have demonstrated that all major subtypes of NSCLC tumors express CXCR4 and that the main sites of lung cancer metastasis, including bones, liver, adrenal glands, and brain, express high levels of CXCL12." (PMID 37227446, 2023). "The significant role of CXCR4 in cancer development has led to this receptor being implemented as an additional prognostic marker for both lung cancer and PCa patients." (PMID 37489388, 2023). "In cancer, CXCR4 has been found to be overexpressed in a variety of human tumors, including breast, ovarian, and lung cancer." (PMID 37538932, 2023). "CXCR4 has been a consistent marker throughout predominant oncological diseases, including lung cancer and PCa." (PMID 37489388, 2023). "Our findings support a role of COPD-EVs to promote the expansion of MICs in premalignant epithelial cells through HIF-1α-CXCR4 axis activation thereby potentially sustaining lung cancer progression." (PMID 37838700, 2023). "A strong interaction exists between the cell surface receptors and C-X-C chemokine receptor type 4 (CXCR4) in lung cancer." (PMID 36518665, 2022). "Some studies revealed that CXCL12 protein expression levels were significantly higher in metastatic sites than in primary tumor site, which mediated the metastasis of CXCR4-expressing tumor cells in lung cancer." (PMID 35729596, 2022). "A recent study showed that ERβ promotes lung cancer invasion by increasing C-X-C chemokine receptor type 4 (CXCR4) expression." (PMID 36060947, 2022). "Based on this background, we performed this meta-analysis to assess the clinicopathological and prognostic significance of CXCR4 expression in patients with lung cancer." (PMID 35729596, 2022). "JUNB and CXCR4 are expressed in lung cancer patients and their expression correlates with worse prognosis." (PMID 36612166, 2022). "Activation of CXCR4 and STAT3 results in the initiation of multiple signaling pathways, leading to metastasis and angiogenesis in lung cancer; thus, CXCR4 and STAT3 are potential targets for anti-angiogenic therapy." (PMID 35918758, 2022). "It has been reported in an experimental study that blocking CXCR4 inhibited the proliferation of lung cancer cells and the migration to CXCL12." (PMID 35729596, 2022). "We demonstrated that the expression levels of EGFR and CXCR4 on the sEVs well represented the ones in the source lung cancer cells." (PMID 35269297, 2022). "CAF‐secreted stromal cell‐derived factor 1 (SDF‐1) enhances the chemoresistance of lung cancer cells to cisplatin by suppressing CXCR4 expression, suggesting CAFs facilitate drug resistance via the CXCR4‐mediated signaling pathway." (PMID 35603909, 2022). "This is consistent with preceding observations from our own and other groups that markedly increased levels of cytokines, including IL-2, TNFα and CXCR4, are detected in experimental and human lung cancer tissue." (PMID 36241617, 2022).
lung carcinoma (continued). "Lung cancer cells that were treated with 4 μg/mL propofol for 2 h significantly inhibited the lung cancer cell proliferation and led to a decrease in cell viability, which is related to the decrease in CXCR4 expression." (PMID 34990302, 2022). "Although the previous studies have shown the potential prognostic value of CXCR4 in lung cancer, its actual role is still debated." (PMID 35729596, 2022). "Coupled with this, it was found that the overall survival ability of patients with lung cancer was significantly improved following the increase of CXCR4 expression in the tumor stroma." (PMID 35768814, 2022). "Next, to examine the consequences after suppressing the CXCR4 expression in lung cancer cells, we applied the interruption approach using CXCR4-shRNA." (PMID 35064116, 2022). "Regarding the prognostic value of CXCR4 expression, the results of our meta-analysis demonstrate that elevated CXCR4 expression appears to be related to poorer OS in lung cancer." (PMID 35729596, 2022). "Considering the availability of novel studies including a greater number of patients, we performed an updated meta-analysis to evaluate the clinicopathological and prognostic value of CXCR4 expression in lung cancer." (PMID 35729596, 2022). "We observed that CAFs-derived SDF-1 promoted tumour EMT by activation of the CXCR4/β-catenin/PPARδ pathway in lung cancer ADC." (PMID 33637678, 2021). "Simultaneous miRNA modulation reduced metastatic dissemination of lung cancer cells both in vitro and in vivo through CXCR4 inhibition." (PMID 34107168, 2021). "In particular, we investigated the relationship between CAF and activation of the SDF-1/CXCR4/β-catenin/PPARδ signalling pathway within the context of lung cancer ADC." (PMID 33637678, 2021). "In silico analysis also revealed miR‐126‐3p binding sites in the 3′UTR of CXCR4, a well‐known receptor involved in metastatic dissemination of lung cancer cells." (PMID 34107168, 2021). "In the current study, CXCR4 expression levels were higher in lung cancer compared with benign disease, though the differences were not significant." (PMID 34121134, 2021). "Our and others’ research also discovered that high level of CXCR4 expression is also found in stem-like lung cancer cells." (PMID 33414415, 2021). "We also explored the expression of integrin αvβ3 and CXCR4 in different lung cancer subtypes, and compared the neovasculature among these subtypes." (PMID 34121134, 2021). "In this study, we infer that CXCR4 confers resistance to ionizing radiation (IR) in nonsmall cell lung cancer (NSCLC) cells." (PMID 33414415, 2021). "CXCR4 is the most commonly overexpressed and studied chemokine receptor in many different malignant tumors, including lung cancer." (PMID 32457792, 2020). "This coincides with a study recently published in 2019, which observed increased expression of CXCR4 in lung carcinoma." (PMID 33262947, 2020). "Then secreted CXCL12 enters into the blood circulation and directs CXCR4/CXCR7+ lung cancer cells to the sites of targeted organs." (PMID 33129326, 2020). "CXCR4 expression was highly expressed in both normal and lung cancer tissue, and seemed to be higher in cancer tissue." (PMID 33129326, 2020). "We previously identified in NSCLC a subset of CD133+ lung cancer stem cells (CSCs), co-expressing CXCR4, endowed with stemness features and characterized by resistance to cisplatin and superior ability to seed distant site and initiate metastatic process." (PMID 33123122, 2020). "Meanwhile, the results of the expression of CXCR7 and CXCR4 in normal tissue and lung cancer tissue by western blot was consistent with that of immunohistochemical staining." (PMID 33129326, 2020). "Increasing evidence suggests that CXCR4 is potentially the CSCs marker of malignant tumors including synovial sarcoma, endometrial cancer, lung cancer, and so on." (PMID 32232002, 2020).
lung carcinoma (continued). "SDF-1/ CXCR4 interaction was directly responsible for the chemoattraction of lung cancer cells in Boyden chamber assays." (PMID 31330786, 2019). "A role for the CXCL12/CXCR4/7 chemokine–chemokine receptor axes has also been proposed in mouse lung cancer metastasis-induced by lung carcinoma cell transplantation most likely by shaping infiltrated immune cell population and promoting angiogenesis." (PMID 30832375, 2019). "They found that this tracer shows different degrees of uptake in biopsied lung carcinoma depending on the histology, and this result is correlated with CXCR4 expression." (PMID 29725717, 2018). "Recent studies have reported that the SDF-1/CXCR4 axis plays a regulatory role in pulmonary fibrosis, acute lung injury, lung cancer, and other diseases." (PMID 30541517, 2018). "A recent study addressed the possible functional role of CXCR4 in the maintenance of stemness of lung cancer stem cells." (PMID 30060526, 2018). "Experiments carried out on cancer stem cells purified from lung cancer cell lines have suggested that CXCR4 expression on these cells is required for self-renewal activity, resistance to ionizing radiations and for tumorigenicity in vivo." (PMID 30060526, 2018). "Previous studies have reported that CXCR4 is the main cognate receptor of SDF-1, and the SDF-1/CXCR4 biological axis has an important role in many types of solid tumors, including pancreatic, breast, gastric, and lung cancers." (PMID 30337520, 2018). "In this review, the pathologic roles that CXCL12/CXCR4 play in lung cancer propagation are presented." (PMID 30257500, 2018). "MiR-410 elevated the expressions of stem cells markers such as Oct4, Sox2, Nanog, CXCR4 and putative lung cancer stem cells surface marker CD44 and CD166." (PMID 28076327, 2017). "We demonstrate miR-410 increases the levels of stem cells marker Sox2, Oct4, Nanog, CXCR4 as well as lung cancer stem cells surface marker CD44 and CD166." (PMID 28076327, 2017). "Meanwhile, SDF-1α facilitates lung cancer cell proliferation and cisplatin resistance via CXCR4-activated NF-κB and Bcl-xL." (PMID 28851377, 2017). "Further studies found that SDF-1α promotes lung cancer cell proliferation and cisplatin resistance via CXCR4-activated NF-κB and Bcl-xL." (PMID 28851377, 2017). "The overexpression of CXCR4 has been shown to lead to metastasis and increased levels of CXCR4 expression were in particular found in breast and lung cancer cells." (PMID 27812115, 2016). "Reports from our and other labs have shown nuclear localization of CXCR5 and CXCR4 in prostate and, breast and lung cancer respectively." (PMID 25888629, 2015). "Demonstration of in vivo efficacy will advance the development of IL-24/CXCR4 based combinatorial therapeutic interventions for lung cancer." (PMID 25775124, 2015). "In this study, we demonstrated that IL-24-mediated its anti-metastatic activity by disrupting the SDF-1/CXCR4 axis in lung cancer cells." (PMID 25775124, 2015). "In conclusion we have demonstrated that IL-24 exerts its anti-metastatic activity by disrupting the SDF-1/CXCR4 axis and that IL-24-based therapy in conjunction with CXCR4 inhibitors will be more effective in attenuating lung cancer metastasis." (PMID 25775124, 2015). "The interaction between the stroma-derived factor SDF-1α and the increased CXCR4 further enhanced the radiation-induced invasiveness of lung cancer cells through pAkt and pERK1/2 signaling transduction pathways." (PMID 25843954, 2015). "Among the pulmonary cancer entities, CXCR4 has been shown to be highly expressed in primary and secondary lung cancers." (PMID 25671300, 2015). "The stromal cell derived factor (SDF)-1/chemokine receptor (CXCR)-4 signaling pathway plays a key role in lung cancer metastasis and is molecular target for therapy." (PMID 25775124, 2015).
lung carcinoma (continued). "Our data suggest that the EGFR-L858R mutant promotes the expression of CXCR4 in lung cancer cells primarily through the ERK signaling pathway, rather than PI3K-AKT and JAK-STAT3 pathways, thereby increasing invasive ability." (PMID 26338423, 2015). "Ectopic expression of EGFR-L858R in lung cancer cells acted through activation of ERK signaling pathways to induce the expression of CXCR4." (PMID 26338423, 2015). "Inhibiting the SDF-1/CXCR4 axis with a neutralizing antibody or transfection with an antisense oligonucleotide against CXCR4 significantly reduced invasion, migration and adhesion of lung cancer cell lines in vitro." (PMID 25775124, 2015). "Due to its pivotal role, the SDF-1/CXCR4 axis represents a promising target for lung cancer treatment." (PMID 26416452, 2015). "To determine if the observed IL-24-mediated inhibition on CXCR4 was unique to H1299 cells, we conducted experiments in an additional lung cancer cell line, A549." (PMID 25775124, 2015). "Specifically, we found that ectopic expression of EGFR-L858R in lung cancer cells acted through activation of ERK signaling pathways to induce the expression of CXCR4." (PMID 26338423, 2015). "There is increasing evidence to suggest that the CXCL12/CXCR4 chemokine axis is important for the cell invasion and migration of several types of tumor, particularly lung cancer." (PMID 24944647, 2014). "Compared with the untransfected group, the mRNA expression levels of CXCR4 in the A549 human lung carcinoma cell line were downregulated in the CXCR4-siRNA-transfected group." (PMID 24944647, 2014). "Preclinical and clinical studies support the viewpoint that chemokine CXCL12 (stromal cell-derived factor, SDF-1) and it’s receptor CXCR4 play a pivotal role in the progression and metastasis of lung cancers, particularly in non-small cell lung cancer (NSCLC)." (PMID 24897301, 2014). "siRNA-CXCR4 mediated the downregulation of CXCR4 expression in human lung cancer cells and led to a significant decrease in the invasion and migration of A549 cells." (PMID 24944647, 2014). "The proliferation of the A549 lung cancer cell line in response to CXCL12 was found to be reduced by the downregulation of CXCR4 expression by the pBSilence1.1-siRNA-CXCR4 vector, as determined by MTT assay." (PMID 24944647, 2014). "It has been demonstrated that gefitinib-resistant lung cancer cells exhibited strong sphere-forming activity and high CXCR4 expression, and isolated CXCR4-positive cells were responsible for the features of CSCs." (PMID 24489728, 2014). "By contrast, the proliferation of A549 cells was significantly reduced by CXCR4-siRNA, indicating that the downregulation of CXCR4 impaired the ability of the lung cancer cells to grow." (PMID 24944647, 2014). "Reports have shown that SDF-1α/CXCR4 mediated increase in cell migration in lung cancer and osteosarcoma cell lines involve the MEK-ERK-NFkb pathway." (PMID 25514788, 2014). "The analysis confirmed that the CXCL12/CXCR4 biological axis can induce lung cancer cell proliferation." (PMID 24944647, 2014). "In the present study, siRNA-mediated downregulation of CXCR4 expression in human lung cancer cells led to a significant decrease in A549 cell proliferation and invasion." (PMID 24944647, 2014). "The results revealed that the RNAi constructs induced the selective degradation of CXCR4 mRNA and thereby decreased CXCR4 protein expression levels in lung cancer cells." (PMID 24944647, 2014). "Although several studies have assessed the antimetastatic effects of CXCR4 inhibitors in different cancer types, only few have investigated their effects in lung cancer." (PMID 23322021, 2013). "CXCL12 was shown to increase the migration of lung cancer cells through the CXCR4-mediated activation of ERK, which in turn activates IKKa/b and NF-κB, resulting in the activations of integrins (ITGB1 and ITGB3)." (PMID 23322021, 2013).